IL17A (interleukin 17A)
Diseases named in the same sentence as IL17A in open-access papers (continued):
Sharing a sentence is not in itself a finding about the gene and the disease.
oral candidiasis (27 papers, 2011 to 2025). Infection of the mucosal lining of the mouth with the fungus Candida albicans. "In this way, mice deficient in IL-17 signaling components (Il17a−/−, Il17ra−/−, Act1−/− etc.)are particularly sensitive to infections in which prevention is dependent on the action of neutrophils, such as oral candidiasis." (PMID 34220843, 2021). "We recently used these mice to demonstrate that IL-17A is produced by γδ-T and nTh17 cells during the early (two day) response to oral candidiasis." (PMID 26213975, 2015). "Similar mechanisms might be anticipated for the higher frequency of oral candidiasis during treatment with bimekizumab compared to the other antibodies specific to IL‐17A alone." (PMID 38482898, 2024). "There is the IL-17A play vital role in mobilization and activity of neutrophils against infection, and it will be expressed by the activity of Th17 through RORγt and increases the number of neutrophils to inhibit oral candidiasis, even in immunocompromised patients." (PMID 30034167, 2018). "The data presented here provide evidence in a reporter mouse system that IL-17A is not expressed de novo in neutrophils in the context of acute oral candidiasis, despite a strong neutrophilic response." (PMID 26213975, 2015). "Thus, there is no apparent production of IL-17A by neutrophils during the acute response to oral candidiasis." (PMID 26213975, 2015).
dilated cardiomyopathy (26 papers, 2012 to 2025). Cardiomyopathy which is characterized by dilation and contractile dysfunction of the left and right ventricles. "IL17A is essential for progression to dilated cardiomyopathy and is also involved in the pathogenesis of acute and chronic vasculitis and angiotensin II-induced hypertension." (PMID 24013901, 2013). "The IL-23/IL-17A immune axis and γδT cells arepotentially promising therapeutic targets after MI to prevent progression toend-stage dilated cardiomyopathy." (PMID 23316306, 2012).
kidney damage (26 papers, 2015 to 2025). "This is therapeutically advantageous, since IL-17A plays a pathologic role in other diabetic complications, such as nephropathy." (PMID 36674854, 2023). "A similar study showed that IgG-Fc desialylation promotes nephropathy in an SLE mouse model in an IL-17A– and IL-23–dependent manner." (PMID 38113112, 2023). "Th17 is a new type of effector CD4+ T-cell in the IL-17 signaling pathway that secretes IL-17A, which can promote the secretion of proinflammatory factors and macrophage infiltration, thereby exacerbating kidney damage in DN." (PMID 35755045, 2022). "A recent experimental study showed that IL-17A is an orchestrator of TLS formation in the kidney, and this formation is associated with intrarenal inflammation, fibrosis, and progression of kidney damage." (PMID 34540858, 2021). "IL-17A KO STZ-treated mice developed more severe nephropathy than STZ-treated wild-type (WT) mice, with increased glomerular damage and renal interstitial fibrosis at 12 weeks." (PMID 33691614, 2021). "Our aim was to investigate whether chronically elevated circulating IL-17A levels could contribute to kidney damage, using a murine model of systemic IL-17A administration." (PMID 31572188, 2019). "The renal immune response was also significantly altered by the GF condition, wherein IL-17A expression was the most affected in GF + AD mice; however, the deletion of this gene did not significantly affect the disease condition in our adenine-induced kidney damage model." (PMID 32859011, 2020). "Thus, IL-17A could be a therapy target for kidney damage, which needs more clinical evidence." (PMID 33391465, 2021). "In addition, there was a positive correlation between total protein levels and the frequency of IL-17A+ CD8+ MAIT cells, whereby reduced total protein levels are a marker of liver and kidney damage." (PMID 36189274, 2022).
adenoma (25 papers, 2013 to 2025). A neoplasm arising from the epithelium. "In line with our findings, IL-17A was proposed to contribute to IL-23-induced adenoma development of duodenal tumors in these models, as IL-17A expression was found to be increased in mice developing tumors." (PMID 40280932, 2025). "In accordance with the data obtained from flow cytometry, immunohistochemistry (IHC) also confirmed an accumulation of IL-17A in FAP tissues, particularly within adenomas and FAP-associated duodenal cancer tissue." (PMID 40280932, 2025). "IL-17A is a cytokine typically produced by Th17 cells, and an increase in the expression of IL-17A can be seen in the adenoma–carcinoma sequence." (PMID 34298598, 2021). "Published data show that chronic inflammation is present in almost all the observed sporadic colorectal adenoma samples and that IL-17A is upregulated since the adenoma stage and its level remains high until the cancer stage." (PMID 34299314, 2021). "In our previous studies, we have demonstrated an elevated expression pattern of IL-17A in the tumor microenvironment of adenoma/CRC." (PMID 28484082, 2017). "IL-17A induced increase in Duox2 expression in FAP adenoma and carcinoma tissues could also be corroborated at the protein level." (PMID 40280932, 2025). "The discovery of an elevated number of these cells in normal FAP tissue indicates that IL-17A(+) NKp44(–) ILC3s may begin to accumulate prior to oncogenic transformation, suggesting their potential involvement in the early stages of adenoma development." (PMID 40280932, 2025). "In FAP adenomas, the IL-17A(+) NKp44(−) ILC3 cells showed increased expression of αEβ7 integrin, which may further enhance their adhesion to subepithelial areas." (PMID 40280932, 2025). "Next, we tested whether IL-17A-producing ILC3 might be involved in establishing the transcriptional program observed in FAP adenomas, thereby promoting oncogenic transformation." (PMID 40280932, 2025). "Considering that IL-17A is upregulated in the adenoma stage and its level remains high at the cancer stage; therefore, an anti-IL-17 treatment may be useful since the adenoma stage." (PMID 34299314, 2021). "We have, for the first time, examined IL-17A dynamics along the human colorectal adenoma-carcinoma spectrum and have found that the expression of IL-17A, at both the mRNA and protein levels, was significantly increased in the adenoma stage and persisted to the CRC stage." (PMID 31637216, 2019). "Our data declare that the IL-17A expression level in both CR adenomas and CRC increases continuously from the adenoma stage to the CRC stage." (PMID 40149674, 2025). "Similar findings were made with respect to DLL1 and DLL4 expression, which was significantly increased in FAP duodenal tissue, with the highest expression in FAP adenomas, while only DLL4 correlated significantly with IL-17A(+)NKp44(−)ILC3 frequency." (PMID 40280932, 2025). "We observe an increase in duodenal IL-17A(+)NKp44(−) innate lymphoid type 3 cell (ILC3) in FAP, localized near the epithelium and enriched in adenomas and carcinomas." (PMID 40280932, 2025). "We demonstrated in vitro that IL-17A leads to an increased expression of DUOX2, which corresponds with the elevated DUOX2 expression observed in FAP adenomas." (PMID 40280932, 2025). "From the adenoma stage to the CRC stage, tumor-promoting relevant cytokines, such as IL-6, IL-8, IL-17A and IL-33, are significantly increased." (PMID 36466926, 2022). "Our data indicate an important role for IL-17A-producing ILC3s in FAP adenomas, however, we did not perform a detailed analysis of the entire immune infiltrate." (PMID 40280932, 2025). "Moreover, significantly higher IL-17A, CD4, and class II MHC transactivator mRNA levels were found in the pituitary glands of patients diagnosed with primary hypophysitis compared with adenoma and normal gland." (PMID 35205804, 2022).
adenoma (continued). "In patients with adenoma and CRC, increased IL-23 has been detected and may function as an upstream factor to regulate the production of IL-17A from TH17 cells." (PMID 36466926, 2022). "Cui and others found IL17a increased from low to high dysplastic lesions, suggesting a positive correlation with tumor progression in early carcinogenesis; no studies have examined Th17 cells in adenomas." (PMID 33987094, 2021). "Nevertheless, our findings suggest that ILC3s, rather than Th17 cells, are the primary source of IL-17A, as most IL-17A(+) cells in FAP adenomas were CD3(−)." (PMID 40280932, 2025).
diabetic retinopathy (25 papers, 2017 to 2025). "For instance, interleukin-17A (IL-17A) plays a role in the early stages of diabetic retinopathy development." (PMID 40332476, 2025). "In terms of inflammatory processes that promote the development of diabetic retinopathy, measurements have shown exceptionally high levels of IL-17A in patients with DME." (PMID 40332476, 2025). "A systematic evaluation and Meta-analysis were performed to determine the relationship between IL-17A levels in ocular aqueous and peripheral venous serum samples and diabetic retinopathy (DR)." (PMID 38711982, 2024). "We and others have found that Interleukin-17A (IL-17A) is a prevalent inflammatory pre-cursor to diabetic retinopathy in Type I diabetic mice." (PMID 36674854, 2023). "In our previous studies, we found that IL-17A played a pivotal role in the onset and progression of diabetic retinopathy in streptozotocin (STZ)-Type I-diabetic mice." (PMID 36674854, 2023). "Considering this timeline, it is evident that these intravitreal injections were performed to determine the role of IL-17A in diabetic retinopathy." (PMID 36674854, 2023). "We and others have found that IL-17A is one of the pivotal inflammatory components that induces retinal pathogenesis, vascular impairment, and the onset of diabetic retinopathy." (PMID 36674854, 2023). "IL-17A has been shown to be an important detrimental cytokine in the progression of diabetic retinopathy." (PMID 36209107, 2022). "Accumulating evidence suggests that IL-17A plays a key role in human retinal degenerative diseases, including age-related macular degeneration, diabetic retinopathy and glaucoma." (PMID 35392087, 2022). "Higher levels of IL-17A have been observed in the blood and intraocular fluids in patients with diabetic retinopathy (DR), in particular those with diabetic macular oedema." (PMID 34769307, 2021). "Collectively, these data suggest that the VAF347 inhibitory impact on both Th17 cell differentiation and IL-17A production played a pivotal role in this potential therapeutic, negating the onset of diabetic retinopathy." (PMID 33919327, 2021). "IL-17A has been reported to exacerbate diabetic retinopathy by impairing the function of Muller cells, which are the major glial cells in the retina." (PMID 33050355, 2020). "In the current study, we provide evidence that the RORγt/IL-17A axis plays a pivotal role in the onset of diabetic retinopathy." (PMID 32429598, 2020). "Intravitreal injections of anti-IL-17A are still a possible therapeutic for diabetic retinopathy that we are further investigating." (PMID 32429598, 2020). "Blocking IL-17A by intravitreal injections with neutralizing antibodies against IL-17A or its receptor slowed diabetic retinopathy progression by impairing retinal Müller cell function." (PMID 31963845, 2020). "Others have also demonstrated a role for IL-17A in retinal neural cell pathogenesis in murine models of diabetic retinopathy." (PMID 32429598, 2020). "Interleukin (IL)-17A is an inflammatory cytokine that has been previously shown to play a pivotal role in the promotion and progression of diabetic retinopathy." (PMID 32429598, 2020). "Supportive evidence from rat models of Streptozotocin (STZ) induced diabetic retinopathy showed suppression with anti-IL-23, anti-IL-17A or anti-IL-17RA antibodies reduced diabetic retinal injury." (PMID 30783187, 2019). "Furthermore, we observed a notable elevation of serum IL‐17A levels in patients with diabetic retinopathy, underscoring its potential role in diabetic microvascular complications." (PMID 39946217, 2025). "Cxcl1 expression was recently shown to be a mediator of neutrophil recruitment and the pathogenesis of diabetic retinopathy, perhaps through pericyte-mediated alterations in retinal vessel barrier function, which may require IL-17a." (PMID 41002438, 2025).
diabetic retinopathy (continued). "Similarly, a pro-inflammatory phenotype in T1DM patients with diabetic retinopathy was reported, marked by increased production of IL-6, IL-10, and IL-17A by myeloid cells, alongside reduced IFN-γ production by T cells." (PMID 41280935, 2025). "So, it is feasible that anti-IL-17A could enhance the efficacy of anti-VEGF treatments for diabetic retinopathy." (PMID 36675261, 2023). "Since this vascular impairment is a hallmark of non-proliferative diabetic retinopathy, these results suggest that anti-IL-17A could be a potentially novel therapeutic for early stage diabetic retinopathy in both Type I and II diabetics." (PMID 36674854, 2023). "The results of this current study provide evidence that anti-IL-17A could be administered via a systemic route and still halt the onset and progression of diabetic retinopathy." (PMID 36674854, 2023). "Many more pre-clinical studies are required to solidify if anti-IL-17A could supplement anti-VEGF treatments for diabetic retinopathy." (PMID 36675261, 2023). "This will help us further determine if anti-IL-17A could be a potentially novel therapeutic for both early and late stage diabetic retinopathy." (PMID 36674854, 2023). "Still, our current data provides evidence that anti-IL-17A could be a potentially novel therapeutic for diabetic retinopathy." (PMID 36675261, 2023). "In our previous studies, we provided evidence that IL-17A could be a good therapeutic target for diabetic retinopathy." (PMID 36675261, 2023). "Additionally, more elaborate pre-clinical experiments are needed to further clarify the validity of anti-IL-17A as a therapeutic for diabetic retinopathy, which goes beyond the scope of this paper but will be the focus of our future studies." (PMID 36674854, 2023). "IL-17A acts as a proinflammatory cytokine that is primarily involved in retinal cell apoptosis and is expected to be a potential clinical target for the treatment of diabetic retinopathy in the future." (PMID 36582230, 2022). "Alternatively, anti-IL-17A could be administered by intravitreal injections, but this would only provide treatment for retinal pathogenesis and diabetic retinopathy." (PMID 33919327, 2021). "A large body of evidence suggests an important role of Th17/IL-17A in diabetic retinopathy." (PMID 31963845, 2020). "Additionally, multiple IL-17A-producing cells that have been shown to play a role in the onset of diabetic retinopathy such as, microglia, neutrophils, and Th17 cells express RORγt." (PMID 32429598, 2020). "Additionally, IL‐17A was elevated in individuals with diabetic retinopathy (DR)." (PMID 39946217, 2025). "Our future studies will focus on a combined treatment of anti-IL-17A and anti-VEGF in late-stage diabetic retinopathy and neovascularization." (PMID 36674854, 2023). "When IL-17A was systemically ablated in transgenic IL17A−/− STZ-diabetic mice, the progression of retinal vascular impairment and the onset of diabetic retinopathy was halted." (PMID 36674854, 2023). "In diabetic retinopathy 34 genes including AP15, GRB2, IL17A, PLXDC1, C5 and L1CAM were studied in a single year in which, C5 and L1CAM are reported as recently as in 2016." (PMID 28761062, 2017). "Further supporting the role of IL17, IL17A levels were significantly higher in the vitreous of PDR compared to those with non-diabetic retinopathy (non-DMR)." (PMID 40136531, 2025). "Taken together, we postulated that AhR agonist VAF347 will halt Th17 cell differentiation and IL-17A production, which will ameliorate retinal inflammation, and halt the onset of non-proliferative diabetic retinopathy in STZ-diabetic mice." (PMID 33919327, 2021). "Likewise, IL-17A, IL-6, and TNF-α are the primary cytokines involved in retinal inflammation, retinal vascular impairment, and the progression of diabetic retinopathy." (PMID 33919327, 2021).
diabetic retinopathy (continued). "Hence, all therapeutic targets that could halt IL-17A production and IL-17-dependent retinal pathogenesis could be a potential therapeutic that could enhance the efficacy of anti-VEGF treatment, and delay the onset of diabetic retinopathy." (PMID 32429598, 2020).
ischemia (25 papers, 2013 to 2025). A hypoperfusion of the BLOOD through an organ or tissue caused by a PATHOLOGIC CONSTRICTION or obstruction of its BLOOD VESSELS, or an absence of BLOOD CIRCULATION. "As previously reported, IL-17a-releasing γδ T cells peak on day 3 after the onset of ischemia, and IL-17a seems to have a crucial role in the maturation of brain infarction." (PMID 35432162, 2022). "For inflammatory cytokines, on day 14, intramuscular transplantation of hiPSC-MSCs in the MSC-Saline, MSC-MSC/once, MSC-MSC/week and MSC-MSC/3 days groups significantly decreased IL-1A and IL-17A compared with the ischemia group (all p < 0.05)." (PMID 36008710, 2022). "Important cytokines with pro-inflammatory effects, which appear in the brain as a result of ischemia, are interleukin 17A (IL-17A) and interleukin 23 (IL-23)." (PMID 31514749, 2019). "In this study, we used an in vivo model of partial hepatic ischemia/reperfusion injury (IRI) to investigate the role of the γδ-Τ-cell receptor (γδTcR) and the role of IL17a in the pathogenesis of liver injury." (PMID 36902538, 2023). "The serum levels of interleukin (IL)-17A and IL-21 were decreased, and the expression of JAK2/STAT3 proteins was inhibited in all RJQM treatment groups compared to the ischemia group." (PMID 36034959, 2022). "Although we intervened with anti-IL-17A antibodies at different HIRI stages in an attempt to counteract the pro-inflammatory effects of IL-17A, interventions at the end of ischemia and 1 h of reperfusion were not as effective as earlier (pre-ischemic) strategies." (PMID 38494504, 2024).